KRAS (KRas proto-oncogene, GTPase)
Diseases named in the same sentence as KRAS in open-access papers (continued):
Sharing a sentence is not in itself a finding about the gene and the disease.
tumor (continued). "Given the relevance of concurrent mutations in mut KRAS LUAD prognosis and response to therapy, we explored the association of PITPNC1 expression with prevalently mutated tumour suppressor genes (TSGs)." (PMID 37210549, 2023). "‐ KRAS‐targeted long peptide vaccine: peptide vaccine containing a mixture of long peptides derived from tumor‐specific mutant forms of the KRAS antige." (PMID 37039257, 2023). "Presence of a KRAS mutation in a MSI tumour was less likely, 15% in MSI versus 41% in microsatellite stable (MSS) tumours (p = 0.009)." (PMID 37344790, 2023). "Additional subclones with loss of function (LOF) mutations in JAK proteins were also seen, further implicating the role of IFN-γ and the adaptive immune response as major determinants of successful anti-tumour responses in KRAS-mutant malignancies." (PMID 36864508, 2023). "Oncogenic KRAS has long been known to drive the expression of numerous cytokines and chemokines that promote an immunosuppressive tumor microenvironment (TME)." (PMID 37581538, 2023). "By testing serial dilutions of tumor DNA samples with Tier I/II variants (BRAF V600E, KRAS G12C, and EGFR exon 19 deletion p.L747_E749del), the LOD for accurate and reproducible variant calling was determined to be 5% of variant allele frequency." (PMID 37483495, 2023). "In vitro analyses and syngeneic mouse models have shown that NS-1 impairs KRAS signaling, resulting in significant anti-tumor activity." (PMID 37894382, 2023). "Immunofluorescence (IF) staining revealed that KRAS localized predominantly to the cytoplasm in the matched mucosa and KRAS wild-type (WT) tumor." (PMID 37051535, 2023). "Sym004 has shown clinically meaningful rates of PR (13%) and minor tumor regression (44%) of target lesions in the Phase I trial (NCT01117428) in patients with KRAS WT mCRC and acquired resistance to anti-EGFR inhibitors." (PMID 38269272, 2023). "A previous study showed that a moderate decrease in the KRAS protein is enough to inhibit tumor growth via the stronger inhibition of downstream signaling." (PMID 37513471, 2023).
tumor (continued). "Another interesting concept involves trials investigating mRNA vaccines that target Kirsten rat sarcoma viral oncogene homolog (KRAS) mutations, which are frequent genetic alterations in several neoplasms." (PMID 38067293, 2023). "CRISPR/Cas9-mediated knockout of Rason in mouse embryonic fibroblasts inhibits KRAS-mediated tumor transformation." (PMID 36241718, 2023). "Non-A-on label biomarkers (A-off label, B-on label and B-off label) showed a modest and tumour-type-dependent metastatic increase, which was mainly linked to the increased alteration frequency of KRAS exon 2 mutations and CDKN2A loss in advanced tumour stages." (PMID 37165194, 2023). "Following genetic KRAS silencing, HDAC5 upregulation causes remodelling of the TME via SOCS3-dependent upregulation of CCL2 and CCL7, and recruitment of immunosuppressive tumour-associated macrophages (TAMs)." (PMID 36864508, 2023). "In an intriguing study by Lee and colleagues, the tumor growth in the KRAS-mutant mouse tumor model was two times higher in high-fat-consuming mice compared with the control (normally fed) group." (PMID 38001865, 2023). "SHP2 inhibition alone has little effect on reducing KRAS-driven tumor cell growth, but in combination with a MEK inhibitor resulted in synergistic tumor shrinkage." (PMID 36845684, 2023). "COX2 is a downstream target of KRAS and NFkB signaling in tumor cells and promotes the synthesis of proinflammatory prostaglandins that mediate local inflammation." (PMID 37648285, 2023). "Combinatory therapies of KRAS inhibitors with inhibitors of the upstream regulators or downstream effectors have been proven with enhanced anti-tumor activities." (PMID 37221195, 2023). "It detects the mutation of tumor driver genes EGFR and KRAS and the expression of drug resistance proteins ERCC1 and RRM1, respectively." (PMID 37854320, 2023). "KRAS siRNA uptake was observed in >85% of cancer cells isolated from the tumor mass, and tumor growth was suppressed by ~80%." (PMID 37298407, 2023). "KRAS signaling can reprogram tumor cell metabolism to support tumor growth, however this can also influence the composition of metabolites in the TME, which has a major influence on immune cell function." (PMID 37581538, 2023). "Tumor localization has gained importance with the finding that anti-EGFR therapy combined with chemotherapy is more effective in wild-type KRAS, NRAS, and BRAF patients with left-sided primary CRC tumors." (PMID 37628934, 2023). "In the present study, KRAS square grid was the novel tool used for estimating the tumor-stroma ratio." (PMID 37942205, 2023). "However, using univariate analysis, all except KRAS have significant prognostic value, insinuating that the significance is possibly caused by confounding other prognostic factors including sex, smoking status, and tumour differentiation, which, following adjustment, lost their prognostic impact." (PMID 37686122, 2023). "KRAS oncogenes have been identified in almost a quarter of all solid human tumors, including lung, colorectal, and pancreatic carcinomas, three tumor types with some of the lowest survival rates." (PMID 36928090, 2023). "DNA sequencing confirmed that these organoids harbored mutations in CRC genes (APC, KRAS, and PIK3CA) that corresponded to the mutations found in the original tumor." (PMID 37085135, 2023). "That study explored the KRAS-specific effect on triggering tumour cell invasion upon fibroblast stimulation through the HGF-c-MET axis." (PMID 38087207, 2023).
tumor (continued). "This amplification resulted in increased cMET mRNA and phosphorylated cMET protein levels and the now KRAS-independent tumours were shown to be dependent on cMET for their growth and viability." (PMID 37721639, 2023). "For example, differences in APC, BRAF, KRAS, and NRAS are associated with the location of the primary tumor, whereby mutations in KRAS and BRAF seem to result in worse overall survival and the recurrence site in patients with PM." (PMID 37629011, 2023). "Patients with wild-type KRAS tumor status had significantly increased OS compared to those with mutant KRAS tumor status (9.5 months vs. 4.8 months)." (PMID 36980565, 2023). "We further explored the influences of THZ1 on the apoptosis and cell cycle of PDAC cells with different KRAS mutants, and on tumour growth using both cell‐derived xenograft (CDX) and mini‐CDX animal models." (PMID 38037549, 2023). "MEK inhibitors that target other intermediates in KRAS/RAF/MEK/ERK pathways were abrogated in NSCLC tumor ablation as a single agent therapy due to ERK signaling activation." (PMID 36899885, 2023). "Understanding the molecular bases for these differences as well as defining the precise role that KRAS oncogenes play not only in tumor progression, but in tumor maintenance, is a fundamental issue that needs to be properly addressed." (PMID 36928090, 2023). "The immune responses of TCR-engineered Jurkat cells or primary T cells were detected using IL-2 or IFN-γ ELISPOT or ELISA assays after co-culturing with target cells loaded with peptides or tumor cells intrinsically expressing KRAS mutants." (PMID 37828002, 2023). "Higher KRAS expression in CTCs was negatively correlated with tumour perforation (p = 0.029), lymph node status (p = 0.037), distant metastasis (p = 0.046) and overall staging (p = 0.004)." (PMID 36902476, 2023). "The previous results clearly showed that there are changes in the interactome of KRAS mutants that can be of relevance for the initiation, development, and evolution of KRAS tumours." (PMID 37627169, 2023). "As expected, ACO2 depletion in PaTu-8988t cells with depletion of IscU2 or KRAS increased citrate level, suggesting that ACO2 plays a role in regulation of citrate production in tumor cells expressing activated KRAS." (PMID 37488138, 2023). "Our results show that anti-KRAS antibody can indeed be internalized into both ex vivo cultured matched mucosa and tumor cells." (PMID 37051535, 2023). "A trend in responses toward “not a contraindication” was reported for lymph node positive primary tumour, molecular markers (MS stable/KRAS positive/BRAF positive) and raised tumour markers (CEA, CA19.9, CA125)." (PMID 37020095, 2023). "In both human and mouse KRAS-driven tumours, an increase in tumour progression correlates with elevated levels of ROCK1/ROCK2 kinases." (PMID 36175301, 2023). "Mutant KRAS not only transfers intracellular circRNAs to exosomes and regulates exosomal miRNAs, such as increasing the content of miR-100 in exosomes, but also increase the levels of some tumor-promoting proteins, such as KRAS and EGFR, in exosomes." (PMID 37553810, 2023). "Additional recommendations are made with respect to KRAS, MET amplification, NTRK, and tumor mutation burden." (PMID 36634300, 2023). "The co-inactivation of LKB1 and KEAP1 cooperatively promotes metabolic reprogramming in KRAS-mutant tumor, and even in the presence of KEAP1 inactivation, LKB1 inactivation modulates NRF2 activity through increased ROS levels." (PMID 37675220, 2023). "Sotorasib and adagrasib have shown promising results in inhibiting KRAS-G12C and controlling tumor growth." (PMID 37662925, 2023).
tumor (continued). "Suppression in the expression of the KRAS gene resulted in decreased proliferation in tumour cells, enhanced apoptotic effect, and suppressed tumour growth while showing no cytotoxicity." (PMID 36635659, 2023). "Ablation margin was also shown to be an important factor in predicting local recurrence, with a ≥10 mm minimal ablation margin being required to attain local tumor control, especially for patients with mutant KRAS CRLM." (PMID 36980565, 2023). "Here, the authors describe a quantitative functional cancer genomics platform in genetically engineered mice, and uncover complex interactions between tumor suppressors and KRAS, BRAF, and EGFR oncogenes across more than 100 different lung tumor genotypes." (PMID 37828026, 2023). "In contrast, RAS mutant (KRAS, NRAS) tumours (which are more frequent on the left) associate with poor immune infiltration, low inhibitory molecule expression and recruitment of suppressive myeloid cells." (PMID 37251410, 2023). "Our previous study has verified that miroRNA-30b (miR-30b) directly targeted KRAS, acting as a tumor suppressor in CRC." (PMID 36639711, 2023). "Sotorasib was the first selective inhibitor of G12C-mutant KRAS to reach Phase I and Phase II clinicals trials, demonstrating anti-tumor activity, with tolerable toxicity and safety parameters." (PMID 37190303, 2023). "From a biological standpoint, CRC is a heterogeneous disease in which biological covariates such as CIMP, KRAS/BRAF mutation, MSI and tumor location complicate treatment response and patient outcomes." (PMID 37296894, 2023). "Enhanced IL-1 and IL-6 expression has been observed in KRAS-mutant tumours, which leads to upregulation of IDO-1 in TILs via NF-kB and STAT3 signalling." (PMID 36864508, 2023). "Immunohistochemical analyses of tumor sections from patients with KRAS-mutant NSCLC showed correlations between BACH1 and VEGFA and BACH1 and VEGFR2." (PMID 37651203, 2023). "These panKRAS inhibitors were demonstrated to inhibit tumor growth and downstream MAPK signaling in an extensive panel of KRAS-mutated and KRAS-activated cancer cell lines." (PMID 37569406, 2023). "A previous study showed that a moderate decrease in the KRAS protein is enough to inhibit tumor growth via the stronger inhibition of downstream signaling, as we have also demonstrated." (PMID 37513471, 2023). "Further studies on KRAS mutant xenograft mouse model showed an inhibitory effect on the growth of treated CRC tumor cells with the lipophilic bisphosphonates." (PMID 38023258, 2023). "A KRAS G12C was missed by tumor NGS for patient BR360036 but was detected, classified as tumor derived and tracked to determine molecular response." (PMID 37814061, 2023). "Fortunately, with persistent research efforts, there has been a recent paradigm shift in the field of KRAS drug development, with multiple proof-of-concept approaches leading to objective tumor responses and drug approvals." (PMID 37569406, 2023). "Another important finding of our study is that PDE4DIP affects KRAS-mutant CRC tumor growth via PKCε-mediated destabilization of NF1." (PMID 37355626, 2023). "As SHP2 plays a key role in regulating KRAS and downstream MAPK signalling in cancer, several SHP2 inhibitors have entered clinical trials for the treatment of KRAS mutant tumours." (PMID 38102334, 2023).
tumor (continued). "In this system, Cas9 and gRNA complexes of the CRISPR-Cas9 system generate double-strand breaks (DSBs) at target sequences of KRAS mutants, and the disrupted KRAS mutants inhibit tumor growth." (PMID 37391511, 2023). "Beyond cell-based therapies, numerous vaccines have also been developed to target KRAS-mutant tumor antigens." (PMID 37581538, 2023). "We first carried out [18F]FBnTP and [18F]FDG PET–CT imaging on KRAS(G12D)-driven GEMMs to distinguish mitochondrial activity and glucose flux in tumours." (PMID 36922590, 2023). "GATA6-KO mice exhibit extensive ADM and accumulation of adipocytes and, in the context of an active KRas (KRas*;Gata6-/- mice), accelerated tumor development." (PMID 37491420, 2023). "The expression levels of the three KRAS-related miRNAs (i.e. miR-155, miR-206 and miR-143) were obtained from diagnostic FFPE tumor samples." (PMID 38130990, 2023). "As expected, the treatment of mucosa and tumor cells with anti-KRAS antibodies led to a decrease in SOX9 expression." (PMID 37051535, 2023). "Our study reveals the mechanisms of presentation and TCR recognition of KRAS-G12V mutant peptide and describes TCRs with therapeutic potency for tumor immunotherapy." (PMID 37828002, 2023). "Because the specific inhibitor for KRAS G12D is still in the pre-clinical stage, identifying essential downstream targets in KRAS G12D-driven tumor is critical." (PMID 37041291, 2023). "For example, the inactivation of NF1—a positive regulator of KRAS GTP to GDP transition—should shift KRAS proteins into their GTP-bound state and increase tumor number and/or growth in the KRAS G12C-, KRAS G12D- and EGFR-driven tumors." (PMID 37828026, 2023). "The present findings improve the understanding of the link between oncogenic KRAS and the immune tumor microenvironment." (PMID 36599679, 2023). "The results showed that VAF of some mutations in tumor tissues are significantly higher than those in plasma, e.g. EGFR p.Leu858Arg, KRAS p.Gly12Cys and ALK." (PMID 37004022, 2023). "This revealed increased levels of dihydroorotate, and other intermediates of de novo pyrimidine synthesis in APC and APC KRAS tumours." (PMID 37580540, 2023). "In conclusion, this work established a link between mutated KRAS and cytotoxic CD8+ T‐cell tumor infiltration." (PMID 36599679, 2023). "In support of this notion, the shape of the KRAS G12C tumor size distribution 15 weeks post-tumor initiation was similar to that of the KRAS G12D tumor size distribution at the earlier 9-week timepoint." (PMID 37828026, 2023). "We conducted a cross-sectional study of the KRAS and BRAF mutational landscape of patients with CRC, whose tumor specimens were analyzed at a single institution." (PMID 38139338, 2023). "In summary, our data illustrate the importance of SLC25A21 dysregulation in rewiring tumor metabolism in KRAS-mutant CRC and inform therapeutic strategies for targeting CRC with KRAS mutation." (PMID 37937641, 2023). "The system preferentially released the drug at the pH of the tumor microenvironment and significantly inhibited the expression of KRAS in an in vivo transgenic zebrafish model of hepatic cancer." (PMID 37376135, 2023). "GSEA of premalignant livers from LP245/+ compared with LP+/+ revealed that tumor-promoting pathways such as KRAS signaling, MYC, and epithelial–mesenchymal transition (EMT) pathways were enriched in LP245/+." (PMID 38047594, 2023).